PIK3CA (phosphatidylinositol-4,5-bisphosphate 3-kinase catalytic subunit alpha)
Diseases named in the same sentence as PIK3CA in open-access papers (continued):
Sharing a sentence is not in itself a finding about the gene and the disease.
breast cancer (continued). "In contrast, the NEO-ORB trial showed no improvement in the overall response rate (ORR) and pathologic complete response (pCR) with the addition of alpelisib to letrozole in the neoadjuvant setting of either PIK3CA-mutated or wild-type ER+ early breast cancer." (PMID 36901954, 2023). "Sixty-one percent of PIK3CA HM were accounted for by breast cancers, whereas 80% of PIK3CA mutations in patients with breast cancer were HM." (PMID 36934165, 2023). "We have recently shown that organoids derived from breast cancer metastatic lesions carrying PIK3CA mutations can be efficaciously treated with PI3K-a inhibitor, Alpelisib irrespective of the metastatic site." (PMID 37507791, 2023). "Within this group, only four recommendations were of tier 1 clinical evidence level (1x PIK3CA/KRAS-mutated breast cancer, 1x MET-mutated kidney cancer, 1x ALK fusion-positive NSCLC, and 1x BRCA2-mutated pancreas cancer)." (PMID 38136436, 2023). "The PI3Kα-specific inhibitor alpelisib (PIQRAY or BYL-719) recently obtained approval for PIK3CA-mutated hormone receptor-positive advanced breast cancer in combination with fulvestrant, a hormonotherapy." (PMID 36765741, 2023). "For instance, HS‐10352 substantially inhibited the proliferation of human breast cancer cell lines harboring PIK3CA mutations, such as HCC1954 and MCF‐7, in vitro assays." (PMID 38037839, 2023). "The frequency of PIK3CA mutations in patients with luminal breast cancer is 30–50% using digital PCR or next-generation sequencing (NGS)." (PMID 37106324, 2023). "Paxalisib has been discovered in the latest research to dramatically reduce cell survival in PIK3CA-mutated breast cancer brain metastatic cell lines." (PMID 37489050, 2023). "With a 41% prevalence of PIK3CA mutation in our sample, the findings align with other research, considering that the median prevalence of this mutation in breast cancer patients is estimated to be 36%." (PMID 37761256, 2023). "Accumulating evidence supports the prognostic and predictive value of PIK3CA mutations in patients with HER2+ breast cancer treated with anti-HER2 therapies in both the adjuvant and the metastatic settings." (PMID 37469415, 2023). "In the present study, we reported the prevalence of PIK3CA mutations in Taiwanese patients with breast cancer stratified by IHC subtypes using an NGS database." (PMID 37655108, 2023). "Acquisition of PIK3CA mutations, which usually exist in exons 9 and 20, is the most common abnormality in human malignant tumors, including breast cancer." (PMID 37237509, 2023). "To clarify the PI3Kα status for all our breast cancer cell lines, we tested the PIK3CA gene for the most common mutations resulting in two amino acid changes in the helical domain (C1616G and G1633A), and another two in the kinase domain (A3140G and A3140T)." (PMID 36869202, 2023). "Estrogen receptor-positive (ER+) breast cancer represents the largest breast cancer subtype and is often associated with mutations of PIK3CA at substantially higher rates than triple-negative breast cancer (TNBC)." (PMID 36901954, 2023). "In the SOLAR-1 phase III trial, PIK3CA mutated HR+/HER2-breast cancer patients clearly benefit from a therapy with the α-specific PIK3CA inhibitor alpelisib." (PMID 36367572, 2023). "In this study we identified the PIK3CA gene as being the most commonly mutated gene in canine mammary tumors." (PMID 36635367, 2023). "The compelling antitumor activity in combination with trastuzumab in HER2 + trastuzumab-resistant, PIK3CA mutated breast cancer models is at the basis of the ongoing B-Precise clinical trial (NCT03767335)." (PMID 36913051, 2023). "In particular, double PIK3CA mutations in cis occur in 8–13% of breast cancers, which enhance cell proliferation and tumor growth compared with single hotspot mutations." (PMID 37471270, 2023).
breast cancer (continued). "This method, which can be performed easily and inexpensively, has economic benefits given that PIK3CA mutations are clinically measured in over 1 million women with newly-diagnosed breast cancer, per year." (PMID 37106324, 2023). "The FDA approved as companion diagnostic test the Therascreen®, PIK3CA RGQ PCR Kit for the detection of the PIK3CA mutations with the liquid biopsy in breast cancer patients with this setting, based on the results of SOLAR-1 trial." (PMID 36937316, 2023). "Along with exon 9 mutations these are the two most frequently mutated PIK3CA mutations in breast cancer." (PMID 37758711, 2023). "In the final population analysed, there was an enrichment of breast cancers, representing 59 patients (45.4%) and 64 PIK3CA mutations (47.4%)." (PMID 36934165, 2023). "A second AKT1 inhibitor in development, ipatasertib, is currently undergoing phase I evaluation with maintenance pertuzumab and trastuzumab in patients with HER2-positive advanced breast cancer harbouring PIK3CA mutations (NCT04253561)." (PMID 38201451, 2023). "While other studies have developed various canine cell lines originating from mammary tumors, PIK3CA mutation in these established cell lines are yet to be characterized." (PMID 38033642, 2023). "The current study provides a comprehensive view of novel as well as reported single nucleotide variants (SNVs) in PIK3CA gene associated with Indian breast cancer cases." (PMID 37821962, 2023). "PIK3CA is one of these genes, with a prevalence of up to 40% in primary breast cancer, and 75% of PIK3CA mutations correspond to H1047R (35%), E545K (17%), E542K (11%), N345K (6%), and H1047L (4%)." (PMID 37371673, 2023). "By screening a panel of cancer cell lines that harboured PIK3CA mutation, compound 35 was found to be more potent against breast cancer than others." (PMID 36650905, 2023). "Actually, the majority of mouse models with activating GOF PIK3CA mutations have been used to investigate various subtypes of breast cancer and their therapeutic strategies." (PMID 37109059, 2023). "KRAS mutations were observed in colorectal or pancreatic cancer patients, and PIK3CA mutations mainly occurred in breast cancer and uterine cancer." (PMID 36910668, 2023). "A recent retrospective study showed that in the GeparSepto trial, HER2-low breast cancer was associated with a higher frequency of PIK3CA mutations than HER2-zero tumors." (PMID 37264417, 2023). "The current study provides a comprehensive view of PIK3CA mutation associated with Indian breast cancer cases and identified novel as well as reported SNVs." (PMID 37821962, 2023). "Although few CMT samples were investigated in the present study, we found that some PIK3CA mutations occurred that closely matched those observed in human breast cancers." (PMID 38033642, 2023). "In many patients with PIK3CA mutations, those with breast cancer were recommended for clinical trials." (PMID 36251535, 2023). "PIK3CA mutations are also known in other solid tumors such as breast cancer where the PI3K inhibitor alpelisib is currently approved for treatment hormone receptor-positive, HER2-negative disease with progression after first-line therapy." (PMID 36181606, 2023). "For example, the accumulation of PI3K gene mutations in somatic cells also promotes the development of breast cancer and PIK3CA mutations have been found in solid tumors." (PMID 36671478, 2023).
breast cancer (continued). "Inavolisib, in conjunction with palbociclib and fulvestrant, demonstrated preliminary antitumor activity and manageable safety in patients with PIK3CA-mutated breast cancer." (PMID 37489050, 2023). "Eventually, breast cancer cells are associated with activated PI3K/AKT signaling associated with either PIK3CA point mutations or PTEN suppression depending upon the type of breast cancer." (PMID 37415164, 2023). "PIK3CA mutations are significantly associated with breast cancer occurrence and provide a growth advantage to cancer cells, which leads to progression and drug resistance." (PMID 37655108, 2023). "Within this approach, the pharmacologic targeting of PIK3CA mutations in ER+/HER2-advanced breast cancer has recently shown significant benefits after the development of endocrine therapy resistance." (PMID 36825198, 2023). "In a previous study, it was reported that PIK3CA mutations appeared to be linked to AA metabolism in breast cancer, revealing a potential role of the AA pathway in the tumour microenvironment." (PMID 37965796, 2023). "The PIK3CA gene is commonly mutated in human breast cancer, however it is also seen to be mutated in benign breast lesions such as hyperplasia and adenomas." (PMID 36635367, 2023). "Since its discovery, the mTOR molecular pathway has been implicated in the pathogenesis of breast cancer and become a prominent therapeutic target in addition to targeting PIK3CA mutation." (PMID 37237509, 2023). "Alpelisib is effective or human PIK3CA-mutated breast cancer treatment, and a high rate of PIK3CA mutations are observed in both human and canine mammary tumors." (PMID 38033642, 2023). "Here, we describe the design and results of the ring trial for the detection of therapeutically relevant PIK3CA hotspot mutations in HR+/HER2-breast cancer tissue and liquid biopsy (LB)." (PMID 36367572, 2023). "The higher rate of PIK3CA mutations in advanced TNBC relative to early-stage TNBC is likely due to ER expression loss in relapsed breast cancer that was initially positive for ER, a subtype that harbors a high rate of PIK3CA mutations." (PMID 36979714, 2023). "In particular, breast cancer has a relatively low frequency of PIK3CA mutations compared to other cancers." (PMID 38033642, 2023). "MEN1611 and taselisib also induced the degradation of the p110α protein in a dose-dependent manner but only in breast cancer cell lines harboring PIK3CA mutations (H1047R and E545K) independently of HER2 status." (PMID 36913051, 2023). "Based on 55 tumor-normal pairs we identified the PIK3CA gene as the most commonly mutated gene in canine mammary tumors, with 25% of samples carrying mutations in this gene." (PMID 36635367, 2023). "Mutations in PIK3CA, common in approximately 25% of breast cancers, particularly in HER2-enriched tumors, also confer resistance to targeted HER2-based therapies." (PMID 37662839, 2023). "Alpelisib was approved by the U.S. Food and Drug Administration (FDA) in 2019 and is currently used in combination with fulvestrant for the treatment of patients with PIK3CA-mutated breast cancer." (PMID 38033642, 2023). "Other factors, such as the upregulation of CDK6 and CCND1 genes and the mutation of the PIK3CA gene, are known to cause endocrine therapy resistance to breast cancers." (PMID 36831644, 2023). "In a phase II trial in patients with advanced solid malignancies with PI3K/AKT pathway abnormalities, TAS-117 showed anti-tumour activity in patients with PIK3CA H1047R and AKT1E17K-mutated breast cancer and PIK3CA E545K-mutated ovarian cancer." (PMID 37489050, 2023). "There is little data available concerning the description and implications of PIK3CA mutations in metastatic cancer apart from breast cancer (BC)." (PMID 36934165, 2023). "Many studies have suggested that PIK3CA is one of the most frequently mutated genes in breast cancer, especially in the hormone receptor-positive (HR+)/HER2- subgroup." (PMID 38033642, 2023).
breast cancer (continued). "Using the same experimental approach, we examined cell death induced by these inhibitors in the PIK3CA H1047R mutated breast cancer cell line T47D, which is an ideal model for PI3Kα dependency." (PMID 36913051, 2023). "Alpelisib has been developed and used due to the association between human breast cancer and PIK3CA mutations." (PMID 38033642, 2023). "Our study explores the clinicopathological landscape of breast cancer patients who possess the PIK3CA mutation." (PMID 37761256, 2023). "Confirmation of oncogenic driver role of GOF PIK3CA mutations in mouse cancer models and their association with breast cancer subtypes and vascular phenotypes." (PMID 37109059, 2023). "Activating mutations in PIK3CA are reported in around 30% of HER2+ breast cancers and are associated with aggressive tumor behavior and poor treatment outcomes." (PMID 37469415, 2023). "Mutations in PIK3CA are found in approximately 30–40% of breast cancers, with a higher prevalence in HR+/HER2− tumors." (PMID 37176102, 2023). "It has been proved to be safe and efficacious in HR (+), HER2 (-) advanced breast cancer patients harboring PIK3CA mutation." (PMID 37553597, 2023). "Off-target APOBEC activity promotes tumorigenesis by causing oncogenic driver mutations such as PIK3CA E542K or PIK3CA E545K and can contribute to therapeutic resistance to tamoxifen in estrogen receptor-positive breast cancer cells." (PMID 38155930, 2023). "Several breast cancer cell lines with different PIK3CA mutation and HER2 amplification statuses were treated with MEN1611, alpelisib and taselisib." (PMID 36913051, 2023). "Breast cancer cell lines with a wild-type or mutated PIK3CA gene were also assayed, and the IC50 values, in the low micromolar range, were similar to those previously reported for the CH5132799 drug (PA-799)." (PMID 38033496, 2023). "A high frequency of PIK3CA mutations was detected in Taiwanese patients with breast cancer, which was consistent with previous studies." (PMID 37655108, 2023). "PIK3CA mutations have been reported to occur more frequently in breast cancer than in other carcinomas." (PMID 36803941, 2023). "Cumulatively, this indicated variations in the prevalence of PIK3CA mutation based on breast cancer IHC phenotype." (PMID 37655108, 2023). "Only PIK3CA mutation status was an independent predictor for pathological therapeutic effect of NAC in postmenopausal luminal breast cancer patients." (PMID 37106324, 2023). "The hotspot mutation in the PIK3CA gene encoding p110α, H1047R, is the most frequent cancer-specific mutation in breast cancer among others, such as p110αE542K or p110αE545K mutation." (PMID 38134227, 2023). "Activating PIK3CA mutations have also been associated with a lower response rate to neoadjuvant anti-HER2 therapy in patients with early-stage HER2+ breast cancer." (PMID 37469415, 2023). "in Taiwanese patients with breast cancer identified PIK3CA as one of the most frequently mutated genes in 38% of the study population, followed by ERBB2 (23%), ESR1 (10%), AKT1 (6%), and BRCA2 (5%) mutations." (PMID 37655108, 2023). "Results from this phase II clinical trial using MK-2206 alone found that it had limited clinical activity in patients with advanced breast cancer bearing PIK3CA or AKT mutations and PTEN deletion." (PMID 36671478, 2023). "The use of the PI3Kα-specific inhibitor alpelisib (BYL719) for treatment of overgrowth disorders or estrogen receptor–positive breast cancers with activating PIK3CA mutations is a case in point." (PMID 37673340, 2023).
breast cancer (continued). "The purpose of this analysis is to characterize the clinical picture of breast cancer patients with PIK3CA mutation in comparison to the PIK3CA-wild-type group." (PMID 37761256, 2023). "Of these mutations a vast majority (10 of 14) caused the amino acid alteration p.H1047R, homologous to the known PIK3CA hotspot mutation found in human breast cancer." (PMID 36635367, 2023). "One individual had the oncogenic PIK3CA H1047R mutation sensitive to alpelisib, a PIK3CA inhibitor approved to treat PIK3CA‐mutated advanced breast cancer." (PMID 36999792, 2023). "The sonographic features of PIK3CA-mutated breast cancers were strongly associated with extensive and liquefied necrosis." (PMID 38025526, 2023). "Here, we report the results from a single-center observational study that investigated the frequency of PIK3CA mutations in Taiwanese patients with all subtypes of breast cancer using NGS over a period of 24 months." (PMID 37655108, 2023). "Several groups initiated a large number of analyses and demonstrated that PIK3CA mutations were most commonly found in breast cancer." (PMID 37237509, 2023). "Based on available knowledge, the PI3K/Akt/mTOR pathway is overactivated due to the PIK3CA mutations in up to 70% of brain metastases in patients with breast cancer." (PMID 37046703, 2023). "The aim of this study was to analyze PIK3CA mutations in exons 9 and 20 in breast cancers (BCs) and their association with clinicopathological characteristics." (PMID 37195967, 2023). "Breast cancers frequently harbor mutations in the phosphoinositide 3-kinase (PI3K)/mechanistic target of Rapamycin (mTOR) pathway with activating mutations in PIK3CA or loss of function mutations in PTEN, together occurring in over 70% of cases." (PMID 37264081, 2023). "In approximately 40% of patients with HER2‐negative/HR‐positive breast cancer tumors, the PIK3CA gene is mutated." (PMID 38148576, 2023). "Polytherapy with Alpelisib (PIK3CA inhibitor) and Fulvestrant (estrogen receptor antagonist) can improve the survival rates of patients with breast cancer contaning PIK3CA mutations." (PMID 36959802, 2023). "Taselisib, in combination with fulvestrant, has previously undergone phase III clinical trials for the treatment of ER+, HER−, PIK3CA-mutated, advanced breast cancer." (PMID 36671478, 2023). "The SANDPIPER study generated one of the largest clinico‐genomic datasets of patients with ER+, HER2−, PIK3CA‐mutated breast cancer treated with a PI3K inhibitor." (PMID 36892268, 2023). "This includes the PIK3CA mutation found in breast cancer patients, which activates the PI3K/Akt/mTORC1 pathway." (PMID 36834476, 2023). "From the Catalogue Of Somatic Mutations in Cancer (COSMIC) database it is evident that PIK3CA is mutated less frequently in more aggressive breast cancer subtypes." (PMID 36635367, 2023). "Targeting the PI3K pathway has emerged as a promising therapeutic strategy for breast cancer patients with PIK3CA mutations." (PMID 37176102, 2023). "have analyzed 1,918 tumors from 1,756 breast cancer patients, of which 443 samples of ER+/HER2- breast cancer had PIK3CA mutations." (PMID 37251941, 2023). "A previous study showed that patients with HER2 + breast cancer with an activating PIK3CA mutation had lower pathologic complete response (pCR) rates and shorter PFS with palliative HER2-targeted therapy." (PMID 37336919, 2023). "PIK3CA mutations have emerged as a point of interest in breast cancer diagnosis and treatment—especially since the advent of targeted therapies and the 2019 approval of alpelisib." (PMID 37761256, 2023).